TK1 (thymidine kinase 1)
Description:
Cell-cycle-regulated enzyme of importance in nucleotide metabolism. Catalyzes the first enzymatic step in the salvage pathway converting thymidine into thymidine monophosphate. Transcriptional regulation limits expression to the S phase of the cell cycle and transient expression coincides with the oscillation in the intracellular dTTP concentration (Probable). Also important for the activation of anticancer and antiviral nucleoside analog prodrugs such as 1-b-d-arabinofuranosylcytosine (AraC) and 3c-azido-3c-deoxythymidine (AZT).
Tractability: Small molecule: a structure with a bound ligand is known; a high-quality ligand is known; it has a high-quality binding pocket; it belongs to a druggable protein family. PROTAC: UniProt records ubiquitination sites on it; ubiquitination databases record sites on it; a small molecule that binds it is known.
Target class: Enzyme; Transferase
Chemical probes: IDOXURIDINE
Gene: Protein-coding gene on chromosome 17 (78,172,780 to 78,187,233, reverse strand). Ensembl gene ENSG00000167900.
Subcellular location: Cytoplasm
Pathways (Reactome):
Cell Cycle: G1/S-Specific Transcription
Metabolism: Pyrimidine salvage
Gene Ontology:
Molecular function: identical protein binding; protein binding; thymidine kinase activity; zinc ion binding; ATP binding
Biological process: DNA synthesis involved in mitotic DNA replication; protein homotetramerization; thymidine biosynthetic process; thymidine metabolic process; dTMP salvage; nucleobase-containing compound metabolic process
Cellular component: cytosol; cytoplasm; nucleus
Genetic constraint (gnomAD): Loss-of-function variants: 11 observed, 17.93 expected, observed/expected ratio (o/e) 0.61, 90% interval 0.38 to 1.01. The upper end of that interval is the gene's LOEUF score, 1.01, which puts it in group 4 of 6, group 1 being the genes least tolerant of losing a copy. Missense variants: 217 observed, 268.66 expected, observed/expected ratio (o/e) 0.81, 90% interval 0.72 to 0.9. Synonymous variants: 120 observed, 105.34 expected, observed/expected ratio (o/e) 1.14, 90% interval 0.98 to 1.33.
Homologues: Orthologues: chimpanzee TK1 (100% identical), macaque TK1 (99% identical), dog TK1 (92% identical), rabbit TK1 (91% identical), guinea pig TK1 (90% identical), rat Tk1 (88% identical), mouse Tk1 (87% identical), pig TK1 (86% identical), zebrafish tk1 (68% identical), tropical clawed frog tk1 (66% identical), Caenorhabditis elegans thk-1 (43% identical).
Diseases named in the same sentence as TK1 in open-access papers:
TK1 is named in the same sentence as 127 diseases in open-access papers, as found by Europe PMC text mining. Sharing a sentence is not in itself a finding about the gene and the disease. The quoted sentences say what the papers report.
breast carcinoma (57 papers, 1988 to 2026). "Gene-disease associations further prioritized G6PD, SLC2A1, and TK1 as robust targets strongly linked to lung and breast cancers." (PMID 42241400, 2026). "The elevated expression of Thymidine Kinase 1 (TK1) is associated with more aggressive tumor grades, including breast cancer." (PMID 38033034, 2023). "The high pretreatment serum TK1 levels in breast cancer patients were associated with poor OS and DFS." (PMID 32202305, 2020). "In conclusion, our study found that high pretreatment serum TK1 levels in breast cancer patients was associated with poor OS and DFS." (PMID 32202305, 2020). "Given that unregulated proliferation is the hallmark of neoplasia, TK1 is a valuable serum marker for breast cancer, non-Hodgkin’s lymphoma, plasmacytoma, and lung cancer." (PMID 29196624, 2017). "The present report is the first clinical evaluation of a new sensitive and specific immunoassay (enzyme-linked immunosorbent assay, ELISA) for determination of thymidine kinase 1 in serum from breast cancer patients." (PMID 19396699, 2009). "By simultaneously combining three kinds of tumor-associated mRNAs (i.e., C-myc mRNA, TK1 mRNA, and GT mRNA) in breast cancer cells, the triple-interlocked nanomodule could be unlocked for precise drug release." (PMID 35890217, 2022). "Therefore, detection of serum TK1 level can be used as one of the auxiliary diagnostic tests for early breast cancer." (PMID 32202305, 2020). "Therefore, the histological identification of tumors utilizing TK1 suggests promising prognostic and diagnostic potential in breast cancer tissue." (PMID 22778736, 2012). "Increased TK1 protein levels were found to serve as a biomarker for poor prognosis after initial chemotherapy of lung, ovarian and breast cancer." (PMID 37024667, 2023). "A breast cancer tissue array of patient samples verified results we saw in vitro and indicated that ductal and lobular breast cancer progression is influenced by elevated TK1 expression." (PMID 38033034, 2023). "Studies have shown that the prognostic model genes TK1, LOX, KDM5B, PSMD4, and NFE2L3 are associated with breast cancer progression, prognosis stratification, and clinical drug resistance." (PMID 37767092, 2023). "This network showed that 23 of these factors are known to either directly or indirectly interact with TK1 and therefore likely play a role in the observed phenotypic changes between our wild-type and TK1-knockout breast cancer cell lines." (PMID 38033034, 2023). "Our Western Blots indicated that metastatic breast cancer cell lines contained higher levels of TK1 when compared to primary breast cancer cell lines (p <0.05)." (PMID 38033034, 2023). "Prior work has indicated that TK1 is a key player within a network of proteins that affects cellular invasion in breast cancer and tumor progression in both prostate and adrenocortical carcinoma." (PMID 38033034, 2023). "Our findings validated our in vitro analyses and additionally suggest that ductal and lobular breast cancer progression is affected by TK1 expression." (PMID 38033034, 2023). "In this study, we aimed to explore the relationship(s) between TK1 expression and cancer-promoting pathways involved in breast cancer pathogenesis." (PMID 38033034, 2023). "Meanwhile, TK1 activity was found to be significantly higher in patients with breast cancer (BC) than in healthy women." (PMID 37767092, 2023). "Further evaluation of the role that cytosolic TK1 plays in the tumor environment and its influence on breast cancer progression is essential in understanding its potential as both a cancer biomarker and a potential therapeutic target." (PMID 38033034, 2023). "In this study, we aim to explore the relationship of TK1 expression to cancer-promoting pathways involved in breast cancer pathogenesis." (PMID 38033034, 2023). "TK1 upregulation was indicated as an early event in a study of breast cancer and further studies demonstrated a positive correlation between TK1 and cancer stage." (PMID 35559045, 2022).
breast carcinoma (continued). "In breast cancer sera (n = 56), the TK1 protein levels were in the range of 0.14–11.7 ng/mL (mean ± SD = 0.75±1.70 and median = 0.41) and were significantly higher than levels in sera from blood donors." (PMID 36201558, 2022). "Meanwhile, serological TK1 protein assays can distinguish early-phase cancer formation in prostate and breast cancer more usefully than serological TK1 activity assays." (PMID 35559045, 2022). "This study reports the isolation and evaluation of human single domain antibodies against TK1 and their binding to the tumor proliferation biomarker TK1 on lung, colon and breast cancer cells." (PMID 35239730, 2022). "In particular, in in vitro models of lung and breast cancers, dTTP produced by TK1 was demonstrated to allosterically activate the enzyme Ribonucleotides Reductase (RNR), which converts GDP to deoxiGDP." (PMID 34830698, 2021). "Emerging data support the use of thymidine kinase 1 (TK1) activity as a prognostic marker and for monitoring of response in breast cancer (BC)." (PMID 33714010, 2021). "The high serum TK1 was an independent predictor of poor survival in breast cancer patients with T2DM." (PMID 32202305, 2020). "At present, studies have proved that TK1 expression level is positively correlated with tumor load in gastric cancer, lung cancer, early breast cancer and other cancers." (PMID 32202305, 2020). "The present study indicated that the high serum TK1 was associated with poor OS and DFS in breast cancer patients with T2DM." (PMID 32202305, 2020). "TK1 levels were measured in breast carcinoma patient tissue samples including simple carcinoma, infiltrating ductal carcinoma, medullary carcinoma, and sclerosing carcinoma." (PMID 33292474, 2020). "TK1-supported tumor growth has been shown in lung adenocarcinoma and breast cancer cell lines; bioinformatical evidence suggests similar TK1 influence in adrenocortical carcinoma and prostate cancer patients." (PMID 33292474, 2020). "They assumed that TK1 and Ki-67 probably are two independent proliferation index of breast cancer cells." (PMID 32202305, 2020). "Studies on the relationship between TK1 expression in tissues and clinicopathological factors and other tumor markers of breast cancer have been reported, but the results still remain controversial." (PMID 32202305, 2020). "Our results indicated the TK1 was a biomarker of poor prognosis in breast cancer and provided some support for theory." (PMID 32202305, 2020). "Using immunohistochemistry, TK1 was found to be located on the cellular membrane of the colorectal, lung, and breast cancer cells." (PMID 32064235, 2019). "We evaluated TK1 gene expression using RNA-sequencing data from TCGA in breast cancer patient available data for which hormone receptor status was available." (PMID 30214377, 2018). "Serum TK1 activity is a promising pharmacodynamic marker of palbociclib in ER+ breast cancer, and its value in predicting response to CDK4/6 inhibitors warrants further investigation." (PMID 29162134, 2017). "The value of TK1 as a cell proliferation marker was initially explored using IHC to study human breast cancers." (PMID 29162134, 2017). "DiviTum serum TK1 activity has been explored as a prognostic marker in solid tumors, including breast cancer." (PMID 29162134, 2017). "Serum samples from 53 healthy individuals and 124 breast cancer patients were analyzed for serum TK1 activity and TK1 protein levels, as described in the “Materials and methods” section." (PMID 27079872, 2016). "The results reported here strongly suggest that the TK 210 ELISA is able to detect a significant differences in the levels of the TK1 protein in sera from breast cancer patients in the T1, T2, and T3 stages compared to healthy." (PMID 27079872, 2016). "In ROC curve analysis, the TK 210 ELISA as well as CA 15-3 showed superior sensitivity compared to TK1 activity assay in patients with T2 stage breast cancer." (PMID 27079872, 2016).
breast carcinoma (continued). "The performance of the TK1 activity assay, TK 210 ELISA, and CA 15-3 with sera from patients with all stages of breast cancer were evaluated by constructing ROC curves." (PMID 27079872, 2016). "Even though TK1 activity levels show a correlation with the stage of breast cancer disease, the overall sensitivity of the assays is rather low i.e., less than 35 %." (PMID 27079872, 2016). "Significantly higher serum TK1 protein levels were found in sera from breast cancer patients compared to healthy, and the protein concentration ranged from 0.17 to 9.9 ng/ml (mean ± SD = 1.0 ± 1.9)." (PMID 27079872, 2016). "Previous studies demonstrated that in sera from patients with leukemia, gastric and breast cancer and healthy controls, there was a significant correlation between TK1 protein concentration and TK1 activity." (PMID 25881026, 2015). "In serum from the breast cancer patient, 90% of total TK1 activity eluted in fractions corresponding to MWs of 300-720 kDa with two minor peaks observed in the MW range 200-50 kDa." (PMID 25881026, 2015). "The most important finding in this study was that when sera from dogs with mammary tumors, melanomas, and mastocytomas were analyzed with the two TK1 assays, we observed that only 10 out of 55 dogs showed increased TK1 activity levels compared to healthy dogs." (PMID 26366881, 2015). "A recent study was done on comparison of TK1 molecular forms in sera from healthy dogs, dogs with leukemia and mammary tumors." (PMID 25881026, 2015). "Thymidine kinase 1 (TK1) is a deoxyribonucleic acid (DNA) precursor enzyme and a proliferation biomarker used for prognosis and treatment monitoring of breast cancer in humans." (PMID 25293656, 2014). "In the western blot analysis of native serum TK1 from breast cancer patients prior to treatment, only one band corresponding to human TK1 was observed, demonstrating the high specificity of the anti-TK1 IgY antibody." (PMID 24649267, 2013). "From the progressive breast array, it can be seen that in many cases of breast cancer, TK1 is upregulated in precancerous tissue and remains elevated in correlation to cancer stage." (PMID 22778736, 2012). "The recent development of antibodies against human TK1 has enabled the determination of serum TK1 protein levels in different hematologic and solid tumors such as bladder carcinoma, breast carcinomas, and non-small cell lung cancer." (PMID 22741536, 2012). "Known breast cancer susceptibility genes like TPX2, AURKA, TK1 and BIRC5 are among the top 7 global drivers (the other 3 top drivers are GINS2, COX4NB and NUP93)." (PMID 21806811, 2011). "In conclusion, the current study has demonstrated that the serum concentration of TK1 is increased in patients with breast cancer." (PMID 19396699, 2009). "The effects of 5-fluorouracil (5-FU), doxorubicin and paclitaxel on FDG and FLT uptake were measured in MDA MB231 human breast cancer cells in relation to cell cycle distribution, expression and enzyme activity of TK-1." (PMID 18665170, 2008). "Serum TK from 20 patients with breast cancer and 19 control patients was further assayed to ascertain the relative contributions of the thymidine kinase isozymes TK1 and TK2 to total TK levels." (PMID 3408646, 1988). "As the expression of PGRMC1 and TK1 are associated with proliferation in human breast cancers, we next asked whether PGRMC1 expression was associated with the expression of TK1." (PMID 39804138, 2025). "Upregulated TK1 enzyme activity in serum has been reported in many patients with solid tumors, including thyroid carcinoma; gastric; ovary; prostate and breast cancers." (PMID 39006942, 2024). "TK1 is located on the outside of the cellular membrane of colorectal, lung, and breast cancer cell lines, and cell lines from hematological malignancies, e.g., Raji cells (Burkitt's lymphoma), HL60 cells (promyelocytic leukemia), and Jurkat cells (acute lymphoblastic leukemia)." (PMID 39006942, 2024).
breast carcinoma (continued). "Thymidine kinase-1 (TK1), lysyl oxidase (LOX), lysine demethylase 5B (KDM5B), proteasome 26S subunit non-ATPase 4 (PSMD4), and nuclear factor erythroid 2-like 3 (NFE2L3) genes are implicated in relapse and poor prognosis of patients with breast cancer." (PMID 37767092, 2023). "Based on the patterns we evaluated during in vitro testing and validated with patient data, we hypothesized that metastatic breast tissue contained higher levels of TK1 when comparing primary breast cancer tissue to normal breast tissue." (PMID 38033034, 2023). "Consequently, we compared the DNA methylation levels for the TK1 promoter between invasive-breast cancer cells and healthy cells." (PMID 38033034, 2023). "Additionally, we selected HCC 1806 cells initially because we were curious if an aggressive primary based breast cancer cell line would be pathogenically altered through changes in TK1 expression." (PMID 38033034, 2023). "Moreover, TK1 acts as a predictive marker for several cancer types, including breast cancer and gastrointestinal cancer." (PMID 35311151, 2022). "Furthermore, anti-TK1 antibodies induced cytolysis of lung and breast cancer cells by effector cells demonstrating the potential to be used as immunotargeting agents to eliminate high TK1 expressing tumor cells in cancer therapy." (PMID 35203388, 2022). "Moreover, the inhibition of HOXC-AS3 in breast cancer cells was observed to induce cell apoptosis via the Y-box binding protein 1 (YBX1)/TK1 axis." (PMID 36613528, 2022). "Similar analysis on breast cancer sera showed that the TK 210 ELISA had a higher sensitivity (sensitivity = 59%) compared to the TK1 activity assay (sensitivity = 47%) at a specificity of 98% although the difference was not statistically significant between the area under curves." (PMID 36201558, 2022). "For the clinical validation, serum samples from patients with hematological malignancies (n = 100), breast cancer (n = 56), prostate cancer (n = 70) and blood donors (n = 159) were analyzed using TK 210 ELISA and TK1 activity by [3H]-deoxythymidine (dThd) phosphorylation assay." (PMID 36201558, 2022). "Similarly, to TK1 protein, the TK1 activity values in breast cancer patients were significantly higher levels compared with blood donors, and they are ranging from 0.98 to 32.5 pmol/min/mL (mean ± SD = 2.92±4.44 and median = 1.98)." (PMID 36201558, 2022). "Importantly, these results are in line with previous reports indicating that increased expression of thymidine kinase-1 (TK1), an enzyme of the pyrimidine salvage pathway, correlates with poor prognosis in breast cancer patients treated with palbociclib." (PMID 32344635, 2020). "The results of the present study showed that the positive rate of TK1 expression in breast cancer patients with tumor diameter > 2.0 cm was higher than those with tumor diameter ≤ 2.0 cm, suggesting that TK1 expression was correlated with tumor size in breast cancer patients." (PMID 32202305, 2020). "Therefore, dynamic monitoring of the activity of TK1 is of certain clinical value in evaluating the tumor progression of breast cancer patients." (PMID 32202305, 2020). "Our study provides the first evidence that serum TK1 activity as early as 2 weeks following CDK4/6 inhibitors is highly correlated with tumor cell proliferation response in patients with early-stage HR+ breast cancer." (PMID 29162134, 2017). "Serum TK1 activity has demonstrated prognostic value in patients with early-stage breast cancer." (PMID 29162134, 2017). "This limits the clinical use of TK1 activity assays in breast cancer patients." (PMID 27079872, 2016). "However, significant correlations were found between the serum TK1 activity and TK1 protein levels in healthy (rs = 0.72, P < 0.0001) and breast cancer patients (rs = 0.60, P < 0.0001)." (PMID 27079872, 2016).